APOE (apolipoprotein E)
Diseases named in the same sentence as APOE in open-access papers (continued):
Sharing a sentence is not in itself a finding about the gene and the disease.
carotid atherosclerosis (39 papers, 2012 to 2025). A thickening and loss of elasticity of the walls of carotid arteries that occur with formation of atherosclerotic plaques. "Herein, we have used a periarterial cuff to generate a progressive carotid atherosclerosis model in apolipoprotein E–deficient mice." (PMID 36481841, 2024). "Building on previous studies, we have used a periarterial cuff to generate a progressive carotid atherosclerosis model in apolipoprotein E–deficient mice." (PMID 36481841, 2024). "In conclusion, our findings obtained from apoE−/− mice provide epigenetic insights into how EZH2 increases the risk of atherosclerotic heart disease." (PMID 27295295, 2016). "Therefore, the aims of this study were, first, to analyze the association of APOE e4 carrier status with carotid atherosclerosis, and second, to analyze the association of CRF with carotid atherosclerosis in APOE e4 carriers." (PMID 36357490, 2022). "The APOE e4e4 genotype was associated with increased carotid atherosclerosis." (PMID 36357490, 2022). "In addition, in apolipoprotein E (ApoE)-deficient mice, the progression of carotid atherosclerosis is accompanied by a decrease in MFN2 levels, and overexpression of MFN2 inhibits oxLDL-induced VSMC proliferation during atherogenesis." (PMID 33240899, 2020). "Recently, alanine was found to be independently associated with major adverse cardiovascular events, but reduced alanine levels were also reported in both apolipoprotein E-deficient mice (apolipoprotein E(−/−) mice) and the plasma of patients with stable carotid atherosclerosis." (PMID 28535803, 2017). "BBR has been reported to suppress carotid atherosclerosis in high-fat diet-established ApoE−/− mice by regulating cell autophagy, proliferation, and apoptosis via PI3K-AKT-mTOR signaling." (PMID 40126149, 2025). "In ApoE−/− mouse models, miR‐155‐5p‐enriched exosomes promoted the occurrence of carotid atherosclerosis by increasing permeable and angiogenic activity." (PMID 39495676, 2024). "Apolipoprotein E (APOE) influences cholesterol levels and certain isoforms are associated with increased carotid atherosclerosis, though the exact association between APOE and carotid plaque is uncertain." (PMID 38034385, 2023). "MCC950 then reduced maximum stenosis, average plaque size, and plaque volume in an ApoE-/- animal model of carotid atherosclerosis, as well as macrophage accumulation and adhesion molecule mRNA expression." (PMID 37765019, 2023). "In the present study, we successfully established a rapid carotid atherosclerosis model by using a high-fat diet and perivascular collar placement in ApoE-/- mice (with a post-surgical survival rate of 100%)." (PMID 27846838, 2016). "In the present study, we report that PVAT derived-APN suppresses lesions formation after collar-induced carotid atherosclerosis through increasing macrophage autophagy in ApoE-/- mice." (PMID 26020520, 2015). "In addition, our study employed a dual approach: a high-fat diet alongside partial ligation of the left carotid artery (PLCA), to precipitate carotid atherosclerosis in ApoE−/− mice." (PMID 39175877, 2024). "After adjusting for several confounders, compared with APOE e3e3, those participants genotyped as APOE e3e4 and APOE e4e4 showed an OR = 1.60 (95% CI 0.45, 5.71) and OR = 4.29 (95% CI 1.16, 15.91), respectively, for carotid atherosclerosis." (PMID 36357490, 2022). "Furthermore, AKT expression was also significantly downregulated in the aorta of the 18 weeks-fed ApoE−/− mice and in the carotid from patients with advanced carotid atherosclerosis." (PMID 36142173, 2022). "Therefore, this strongly suggests that the effects of Alzheimer’s PRS on the phenome (e.g., atherosclerotic heart disease) are likely to be due to biological pathways related to APOE." (PMID 35953482, 2022). "Hence, based on our previous studies and the advantages of UBM, we applied high resolution UBM to observe the effects of SL extract on carotid atherosclerosis in ApoE-/- mice." (PMID 27846838, 2016).
carotid atherosclerosis (continued). "In conclusion, the APOE e4e4 genotype but not the APOE e3e4 genotype was associated with higher carotid atherosclerosis prevalence in men independent of traditional and other atherosclerotic risk factors, supporting the previous observations revealing this association." (PMID 36357490, 2022). "To identify genetic factors contributing to carotid atherosclerosis, we performed quantitative trait locus (QTL) analysis using female mice derived from an intercross between C57BL/6J (B6) and BALB/cJ (BALB) apolipoprotein E (Apoe−/−) mice." (PMID 23463770, 2013). "To confirm the role of lnc_000048 in an in vivo mouse model, we successfully simulated carotid atherosclerosis through partial carotid ligation with or without lentivirus vector infection for the knockdown or overexpression of lnc_000048 in ApoE-/- mice." (PMID 36689133, 2023). "Furthermore, the mechanisms responsible for carotid atherosclerosis could be due to both a decreased serum PON activity and a joint effect of apolipoprotein E (ApoE) and monocyte chemoattractant protein-1 (MCP-1) on LDL." (PMID 38322770, 2024).
hepatocellular carcinoma (39 papers, 2011 to 2025). A malignant tumor that arises from hepatocytes. "Previous studies reported that miR-375 levels correlate with advanced prostate and hepatocellular carcinoma in humans and revealed to be among the most highly differentially regulated blood miRNAs in apoE-deficient mice." (PMID 26013143, 2015). "Previous studies have reported the difference of APOE promoter transcription activities elicited by the −491A/T polymorphism in human hepatocellular carcinoma HepG2 cells." (PMID 22028770, 2011). "Meanwhile, Mφ_APOE cluster, preferentially enriched in tumor tissue, was similar to tumor-associated macrophages (TAMs) in hepatocellular carcinoma (HCC) and the lipid-associated macrophages in adipose tissue by expressing APOE, TREM2, C1QA, and GPNMB30,31." (PMID 35999201, 2022). "Genes associated with lipid metabolism, such as APOA2, APOC3, APOC1, and APOE, were significantly upregulated in multiple cell types of hepatocellular carcinoma, indicating enhanced lipid metabolic activities." (PMID 39944086, 2025). "We demonstrated that MTP-independent ApoE secretion occurs in both human hepatoma cells and physiologically relevant PHHs." (PMID 40180213, 2025). "While MTP-dependent transfer of neutral lipids is dispensable for ApoE secretion, TG biosynthesis, redundantly catalyzed by DGAT1 and DGAT2, is required for efficient ApoE secretion in hepatoma cells." (PMID 40180213, 2025). "While ApoB is essential for initiating lipid recruitment into VLDL particles, our results highlight an important compensatory role for ApoE in preventing excessive TG accumulation in response to defective ApoB secretion in hepatoma cells." (PMID 40180213, 2025). "This compensatory response to ApoB dysfunction activates ApoE expression, at least partially through the upregulation of transcription in hepatoma cells." (PMID 40180213, 2025). "We observed a paradoxical increase in ApoE secretion resulting from increased expression in MTP inhibitor (MTPi)-treated human hepatoma cells." (PMID 40180213, 2025). "The in vivo model used to test the efficacy of this ApoE–liposome system was nude mice bearing xenografts of human hepatocellular carcinoma HepG2 cells." (PMID 36986734, 2023). "In hepatocellular cancer (HCC), APOE transcription was linked to relatively lower levels of immune infiltrates and activation in hepatocellular cancer, while APOE hypermethylation displayed a closer association with immune cell presence in this context." (PMID 38054821, 2023). "The results demonstrated that in the tumor group, the protein expression of APOE was increased for pancreatic adenocarcinoma and hepatocellular carcinoma compared to the corresponding normal tissues." (PMID 37304007, 2022). "It is well-known that siRNA-loaded LNP absorb Apolipoprotein E (ApoE) on their surface, enhancing uptake into hepatoma cells and primary hepatocytes." (PMID 32393755, 2020). "Consistently, knocking out the expression of both ApoB and ApoE dramatically reduced HCV production in hepatoma cell lines, while individual knockouts had only mild phenotypes." (PMID 30871009, 2019). "ApoE and ApoB in gradients of hepatoma cells were detectable within a density range of 1.0856–1.0298 g/ml for Huh7 and 1.0898–1.0272 g/ml for Huh7.5 cells, respectively." (PMID 29497123, 2018). "The effect of H2S on ABCA1 expression and lipid metabolism were assessed in vitro by cultured human hepatoma cell line HepG2, and in vivo by ApoE−/− mice with a high-cholesterol diet." (PMID 27136542, 2016). "This study clearly demonstrates for the first time that HCV utilizes the HSPG-BD region of apoE to associate with SDC4 and thereby infect hepatoma cells." (PMID 24751902, 2014). "Our previous studies demonstrated that the cell culture-grown hepatitis C virus of genotype 2a (HCVcc) uses apolipoprotein E (apoE) to mediate its attachment to the surface of human hepatoma Huh-7.5 cells." (PMID 23844141, 2013).
hepatocellular carcinoma (continued). "Immunofluorescence studies indicate the LRP1-dependent trapping of apoE in EEA1-positive endosomes in human hepatoma cells." (PMID 22238606, 2012). "It has been shown that nuclear proteins from HepG2 (hepatoma) and NB (neuroblastoma) cells can bind to the −491-spanning region of the APOE promoter." (PMID 22028770, 2011). "In HepG2 human liver carcinoma cells, ApoB and ApoE are induced by 24 to 48 h Estrogen treatments." (PMID 32170217, 2020). "Finally, we confirmed HCV strain-dependent ApoE usage in the context of Huh-7.5 hepatocellular carcinoma cells, which are typically used in HCV in vitro studies." (PMID 28659481, 2017). "To test whether the effect of MiTMAB on apoE secretion was specific to macrophages, we measured the effect of MiTMAB on endogeneous apoE secretion from the human hepatoma cell line HepG2." (PMID 25347775, 2014). "This system was proposed for the treatment of hepatocellular carcinoma, which is known usually to express receptors to LDL, thus being capable of binding ApoE." (PMID 36986734, 2023). "Upon incubation of HuH7 hepatoma cells with Cy5-apoE-TRL, fluorescently labelled apoE is efficiently internalized and appears within widely distributed peripheral endosomal compartments." (PMID 22238606, 2012). "However, we found both ApoB and ApoE require nascent biosynthesis of TGs catalyzed by redundant activities of both DGAT1 and DGAT2 for their efficient expression and secretion by the hepatoma cells." (PMID 40180213, 2025). "We found that simultaneous inhibition of both ApoE and ApoB, but not inhibition of either alone, led to TG accumulation in hepatoma cells, indicating that both proteins function redundantly to control TG content." (PMID 40180213, 2025). "We found that while ApoE can be secreted as part of ApoB-containing VLDL particles, secretion of ApoE by itself is strongly activated upon pharmacological inhibition of MTP or genetic ablation of APOB in human hepatoma cells." (PMID 40180213, 2025). "To clarify the relationship between ApoE and MTP activity, we suppressed its function using the MTP inhibitor (MTPi) lomitapide in human hepatoma Huh-7.5 cells, a HuH-7 subline highly active in lipid metabolism, in the presence or absence of oleic acid (OA) that stimulates VLDL secretion." (PMID 40180213, 2025). "The requirement for ATG7 and STX17, and co-localization between APOE and autophagosome marker LC3A that we observe in HepG2 are consistent with previous work showing APOE colocalization and co-immunoprecipitation with LC3 in hepatoma cells." (PMID 34982109, 2022). "In these conditions, secreted virions can be loaded with additional ApoE, by supplementing the viral supernatant with cell supernatant from hepatoma or non-hepatoma cells overexpressing ApoE." (PMID 30871009, 2019).
Down syndrome (38 papers, 2012 to 2026). "This cross-sectional study investigates the associations between apolipoprotein E (APOE) ε4 genotype and attentional abilities across the life span of individuals with Down syndrome." (PMID 32986108, 2020). "Our laboratories and collaborators have focused on the apparently Aβ-independent endosomal pathway changes that are seen in Down syndrome (DS) and as a result of the expression of the apolipoprotein E ε4 allele (ApoE4)." (PMID 31911768, 2019). "Similar efforts are occurring in an extended Colombian family with a PSEN1 mutation, in APOE ε4 homozygotes, and in Down syndrome." (PMID 25217249, 2014). "Individuals with the APOE-ε4 allele had a greater likelihood of having microbleeds than expected for age, suggesting that even in the context of amyloid precursor protein overproduction due to triplication of the 21st chromosome in Down syndrome, APOE-ε4 can still affect disease progression." (PMID 38811657, 2024). "We examined TMCC2 immunoreactivity in late onset AD cases stratified by APOE genotype and age‐matched non‐demented controls, as well as in early onset AD cases associated with mutations in APP or Down syndrome." (PMID 39084860, 2025). "After several decades of study, AD is now considered as a complex disease that results from both genetic and environmental factors, such as age, gender, family history of AD, Down syndrome (DS), and the apolipoprotein E (apoE) gene." (PMID 23762130, 2013). "Few studies have assessed a direct connection between apoE protein levels and AD status, although plasma apoE-related disease-specific phenotypic traits have been investigated in various diseases such as Down syndrome, lung and liver diseases, and in relation to suicide." (PMID 36002891, 2022). "Recent studies have identified some genetic predispositions (just as consanguineous marriage, maternal telomere length, maternal MCM9 polymorphisms, maternal Presenilin-1 and Apolipoprotein E polymorphisms) of women that may cause nondisjunction and Down syndrome birth at younger age." (PMID 36092906, 2022). "Nor did APOE moderate brain age estimates in a prior study of Down syndrome, another genetic form of AD." (PMID 38111006, 2023). "Another study of 30 individuals with Down syndrome reported that APOE genotype did not significantly influence brain-PAD16." (PMID 32001736, 2020).
heart failure (38 papers, 2009 to 2025). Inability of the heart to pump blood at an adequate rate to meet tissue metabolic requirements. "As a model of atherosclerosis-induced heart failure, we applied aged hypercholesterolemic apolipoprotein E-deficient (Apoe-/-) mice with high atherosclerotic plaque load." (PMID 34576047, 2021). "The impact of APOE deficiency on MI-induced heart failure was investigated by performing chronic LAD ligation in 6–8 week old ApoE−/− mice." (PMID 33258000, 2020). "Models were adjusted for demographic variables, apolipoprotein E ε4 alleles, vascular risk factors, depressive symptoms, and heart failure." (PMID 31074810, 2019). "In this study, we have shown that deficiency of apoE could induce heart failure with preserved heart function by development of hypertrophic cardiomyopathy during ageing." (PMID 34816004, 2021). "Further studies involving larger population will be able to answer the question whether major and impactful events could have blunted the effect of such polymorphisms on clinical outcome, as well as to better characterize the relationship between heart failure and APOE gene polymorphisms." (PMID 28840058, 2017). "AD progression is directly correlated with TNFα production in In ApoE-/-, and in clinical studies, circulating levels of TNFα and soluble TNFRs are independent predictors of mortality in patients with heart failure." (PMID 33626069, 2021). "In contrast to B6 mice, 2 months of pressure overload were sufficient to induce signs of heart failure in ApoE-/- mice." (PMID 21711241, 2011). "Altogether the data show that partial inhibition of cellular respiration and subsequent ATP depletion up-regulated the cardiac lipid metabolism and induced signs of heart failure in 5 month-old ApoE-/- mice." (PMID 21711241, 2011). "The microarray analysis also demonstrated that ranolazine reduced the up-regulated fat metabolism of 18 month-old ApoE-/- mice with heart failure." (PMID 21711241, 2011). "Together these data show that two months of pressure overload had induced signs of heart failure in ApoE-/- mice." (PMID 21711241, 2011). "Concomitantly to signs of heart failure, echocardiography showed left ventricular dilation in ApoE-/- mice after two months of aortic constriction." (PMID 21711241, 2011). "As controls, the heart failure-related protein, resistin (Retn), was specifically up-regulated in aortic-constricted mice with signs of heart failure while ApoE was only expressed in B6 mice." (PMID 21711241, 2011). "However, isovolumetric ventricular relaxation time (IVRT) was decreased in old apoE-/- compare wildtype mice, as a sign of heart failure with preserved heart function." (PMID 34816004, 2021). "Our study aims to dissect the involvement of apoE in heart failure." (PMID 34575848, 2021). "However, other studies are necessary to conclude over the role of apoE in cardiac physiology and its involvement in development of heart failure." (PMID 34816004, 2021). "However, further studies are necessary to conclude over the role of apoE in cardiac physiology and its involvement in development of heart failure." (PMID 34816004, 2021). "Overall, our data showed that apoE deficient mice develop mild ventricular dysfunction during aging, even in the absence of high fat diet, which progresses towards heart failure with preserved EF." (PMID 34816004, 2021). "Nanoparticle-mediated delivery of CRMP2 siRNA to ApoE−/− mice with MI resulted in dramatic switch of wound macrophages from M1 to M2 phenotype, marked decrease in inflammation and fibrosis, and significant attenuation of post-MI heart failure and mortality." (PMID 25685072, 2015). "Cardiac function has also been evaluated by inter-breeding apoE-/- and renin-angiotensinogen transgenic (R+A+) mice; in this animal model, heart failure develops with aging, as indicated by the decreased ejection fraction and increased lung weight in aged mice." (PMID 22330242, 2012).
heart failure (continued). "Similarly as did pressure overload (imposed by aortic constriction), depletion of myocardial ATP content by cystamine not only up-regulated the cardiac lipid metabolism but also induced heart failure in ApoE-/- mice within four weeks." (PMID 21711241, 2011). "To understand the pathology of progressive heart failure, we established a model of angiotensin II-induced hypertrophy, which included control, ApoE-/-, and ApoE-/- mice with hypertrophy and a reduced ejection fraction (ApoE-/-angiotensin II group, early heart failure)." (PMID 39198543, 2024). "However, animal models of NICM have demonstrated that senile left ventricular hypertrophy and diastolic dysfunction develop in apoE-deficient mice in the absence of a high-fat diet, finally leading to heart failure." (PMID 38903751, 2024). "For example, ApoE knockout mouse displays severe atherosclerotic phenotype in C57BL/6 compared to FVB/J, whereas, MLP knockout has dramatically increased heart failure rate in the 129/Sv than C57BL/6 genetic background." (PMID 28886070, 2017). "In order to characterize cardiac failure, peak flow velocities in the AAo, Pulm Art, RCA, and LCA were investigated in ApoE-R61h/h mice, before and one week after TAC surgery, by 4D PC MRI and slice-selective 2D PC MRI, respectively." (PMID 25381179, 2015).